KAT6A (lysine acetyltransferase 6A)
Diseases named in the same sentence as KAT6A in open-access papers (continued):
Sharing a sentence is not in itself a finding about the gene and the disease.
anaemia (1 paper, 2025). "Recipients of Kat6a–/–Kat6b+/+ foetal liver cells reached the ethical endpoint within 21 days (p < 10–6), exhibiting anaemia (p = 10–6) and minimal contribution of the foetal liver donor cells to the recipient peripheral blood." (PMID 40000651, 2025).
Arrhythmia (1 paper, 2025). Any cardiac rhythm other than the normal sinus rhythm. "In conclusion, our work documents the occurrence of neonatal arrhythmias and seizures in patients with KAT6A variants." (PMID 41431654, 2025). "In fact, we reported only a single case of a patient with a KAT6A variant presenting with arrhythmias." (PMID 41431654, 2025). "Cardiac arrhythmias during the neonatal period have been rarely reported in association with KAT6A variants, though structural cardiac anomalies are well-documented features of the syndrome." (PMID 41431654, 2025). "Our cases demonstrate that cardiac arrhythmias and seizures can occur in neonates with KAT6A variants, establishing these as previously underrecognized early manifestations of this syndrome." (PMID 41431654, 2025). "Further mechanistic studies and larger cohorts are essential to clarify whether KAT6A dysfunction directly predisposes to arrhythmogenesis or whether observed arrhythmias primarily reflect complications of structural disease." (PMID 41431654, 2025). "While KAT6A’s role in cardiac conduction system development has not been extensively studied, the relatively high background prevalence of SVT in neonates suggests that arrhythmias in patients with both KAT6A variants and structural heart disease may represent multifactorial etiology." (PMID 41431654, 2025).
brachydactyly (1 paper, 2020). A disease characterized by the presence of brachydactyly, including syndromic and non-syndromic forms. "The methylation-related conditions discussed include Wiedemann-Steiner, Kabuki, and Sotos syndromes, and the acetylation-related conditions include Rubinstein-Taybi, KAT6A, genitopatellar/Say-Barber-Biesecker-Young-Simpson, and brachydactyly mental retardation syndromes." (PMID 33488679, 2020).
cleft palate (1 paper, 2025). Cleft palate is a fissure type embryopathy that affects the soft and hard palate to varying degrees. "In mice models, the downregulation of KAT6A affects the expression of several genes associated with the formation of cleft palate, including Dlx1, Dlx2, Dlx3, Dlx4, and Dlx5." (PMID 41357671, 2025). "Both KAT6A‐ or KAT6B‐deficiency and LoF mutations have been shown to lead to facial dysmorphogenesis and cleft palate in some patients, but the specific condition differs to some extent." (PMID 41357671, 2025).
developmental and epileptic encephalopathy (1 paper, 2024). An epilepsy associated with developmental impairment that may be due to either the underlying etiology or the superimposed epileptic activity, or both. "Within the cohort of patients experiencing developmental and epileptic encephalopathy (DEE), WES has revealed genetic variants in novel genes (FGF12, GABBR1, GABBR2, ITPA, KAT6A, PTPN23, RHOBTB2, SATB2) and candidate epilepsy-associated genes (CAMTA1, FAT3, GABRA6, HUWE1, PTCHD1)." (PMID 39523358, 2024).
head and neck squamous cell carcinoma (1 paper, 2025). A squamous cell carcinoma that arises from any of the following anatomic sites: lip and oral cavity, nasal cavity, paranasal sinuses, pharynx, larynx, and salivary glands. "Survival analysis based on online databases revealed that KAT6A was markedly, highly expressed in RCC, cholangiocarcinoma, and head and neck squamous cell carcinoma, which was associated with a favorable overall survival (OS)." (PMID 41357671, 2025). "Examples include KAT6A, which acts as a tumor suppressor in RCC, head and neck squamous cell carcinoma, and SCLC." (PMID 41357671, 2025).
heart abnormalities (1 paper, 2022). "Ventricular septal defects and other congenital heart abnormalities are present in more than 50% of individuals with inactivating mutations in the KAT6A or KAT6B genes." (PMID 36386811, 2022). "KAT6A homozygous deletion mice (KAT6A−/− mice) have ventricular septal defects, and more than 50% of individuals with inactivating mutations in KAT6A or its paralog KAT6B present with ventricular septal defects and other congenital heart abnormalities." (PMID 36386811, 2022).
hepatocellular carcinoma (1 paper, 2024). A malignant tumor that arises from hepatocytes. "As demonstrated by previous studies, KAT6A regulated YAP in hepatocellular carcinoma cell lines HepG2 and Huh7." (PMID 39129034, 2024). "KAT6A is a histone lysine acetyltransferase (also called MOZ and MYST3) belonging to the MYST family, reported to be enriched in the promoter of YAP, which contributed to the progression of hepatocellular carcinoma." (PMID 39129034, 2024).
melanoma (1 paper, 2020). A malignant, usually aggressive tumor composed of atypical, neoplastic melanocytes. "We first validated the on-target gene editing effects of Brd9&Jmjd6 and Kat6a&Jmjd6 dual-crRNAs in RN2c12 and B16-F10c12 melanoma cells." (PMID 32661245, 2020).
Micrognathia (1 paper, 2017). Developmental hypoplasia of the mandible. "Teeth abnormalities and micrognathia are common in patients with the KAT6A p.R1024* mutation." (PMID 31754438, 2017).
myeloid sarcoma (1 paper, 2023). A tumor mass composed of myeloblasts or immature myeloid cells. "This is the second known reported case of KAT6A::EP300 fusion undergoing spontaneous remission in congenital AML or myeloid sarcoma." (PMID 37505185, 2023).
nasopharyngeal carcinoma (1 paper, 2024). A carcinoma arising from the nasopharyngeal epithelium. "The interplay between miR-339-3p, KAT6A, and TRIM24 establishes an axis that plays a crucial role in prohibiting EMT in nasopharyngeal carcinoma cells." (PMID 39160596, 2024). "miR-339-3p was identified as a direct regulator of KAT6A, influencing EMT of nasopharyngeal carcinoma cells." (PMID 39160596, 2024).
osteoporosis (1 paper, 2024). A condition of reduced bone mass, with decreased cortical thickness and a decrease in the number and size of the trabeculae of cancellous bone (but normal chemical composition), resulting in increased fracture incidence. "We also discovered that angelicin dose-dependently increased KAT6A expression and that this increase in turn helped activate the Nrf2/HO-1 antioxidant stress system and ameliorate bone mass loss in oophorectomy-induced osteoporosis model rats by decreasing intracellular ROS levels." (PMID 38956695, 2024).
renal cell carcinoma (1 paper, 2025). "In a patient with renal cell carcinoma (RCC), the fusion of KAT6A with the transcription factor E3, resulting from a chromosomal translocation t(X; 8)(p11.23; p11.21), was detected." (PMID 41357671, 2025).
Salmonella Infections (1 paper, 2021). Infections with bacteria of the genus SALMONELLA. "KAT6A, a lysine acetyl transferase also seen to undergo expression alteration during Salmonella infection in our screen but the alteration was not statistically significant." (PMID 34696686, 2021).
Sepsis (1 paper, 2026). Sepsis is defined as life-threatening organ dysfunction caused by a dysregulated host response to infection. "KAT6A expression is associated with macrophage glucose metabolism, pro-inflammatory responses, and M1 macrophage polarization in sepsis-induced acute lung injury." (PMID 42072730, 2026). "KAT6A expression was upregulated in sepsis and particularly enriched in M1 macrophages." (PMID 42072730, 2026). "The therapeutic potential of KAT6A inhibition was validated in a cecal ligation and puncture (CLP)-induced sepsis model by assessing lung injury, bacterial clearance, and survival." (PMID 42072730, 2026).
ventricular septal defect (1 paper, 2022). The presence of a defect (opening) in the septum that separates the two ventricles of the heart. "Homozygous deletion of the KAT6A gene in mice has resulted in high penetrance of ventricular septal defects." (PMID 36386811, 2022).
cancer (46 papers, 2011 to 2025). A tumor composed of atypical neoplastic, often pleomorphic cells that invade other tissues. "KAT6A functions as a histone acetyltransferase that regulates critical biological processes associated with tumorigenesis, including cancer cell proliferation and metastasis." (PMID 41431654, 2025). "Mutation, gene amplification, and gene fusion of KAT6A and/or KAT6B are associated with oncogenesis, and cancer cell lines that overexpress KAT6A are dependent on this enzyme, strongly suggesting that it is a therapeutic vulnerability." (PMID 39909374, 2025). "The established oncogenic properties of somatic KAT6A alterations (Avvakumov and Côté, 2007) suggest potential cancer predisposition in individuals with germline variants, although this association requires systematic investigation." (PMID 41431654, 2025). "The analysis of the expression profile (GSE108242) obtained from the KAT6A gene knockdown model revealed that the expression of this gene was closely associated with several cancer hallmark-related pathways." (PMID 35422864, 2022). "Chromosomal translocations of oncogenes KAT6A/B encoding for KATs were identified in a variety of cancers and KAT6A accounted for senescent suppression by regulating the suppressors of CDKN2A locus." (PMID 33330071, 2020). "In humans, abnormal chromatin acetylation caused by KAT6A may be a contributing factor to cancer." (PMID 36077605, 2022). "Further we also identify key master cancer regulators like SMAD4, EP300, KAT6A and TAF1 which are associated with multiple cancers and are related to critical oncogenic processes." (PMID 41404623, 2025). "Recently, inhibitors have been developed for both CBP/p30061 and KAT6A/KAT6B30 protein pairs with the view of developing novel cancer therapeutics." (PMID 40000651, 2025). "Here we interrogate a complex-mediated change in the substrate preference of the MYST member KAT6A, a target for cancer therapeutics." (PMID 39909374, 2025). "The dysregulation of KAT6A or KAT6B has been shown to exert a pivotal influence on survival outcomes of a multitude of cancer types, further substantiating their involvement in oncogenesis." (PMID 41357671, 2025). "The frequency of somatic mutations in KAT6A and KAT6B is reported to be relatively high in cancer, with 2.7% in KAT6A and 2.3% in KAT6B, respectively." (PMID 41357671, 2025). "In cancer, inhibition of KAT6A and KAT6B using smallmolecule compounds WM-8014 and WM-1119 induces cell cycle exit and cellularsenescence in an INK4A/ARF-dependent manner." (PMID 39958699, 2024). "In vivo, knockdown of KAT6A not only inhibited cancer growth but also impaired the ability of cancer cells to form metastasis." (PMID 39678497, 2024). "APEX1 promotes multidrug resistance in cancer, enhances KAT6A LLPS, and facilitates interaction between KAT6A and PARP1." (PMID 38973255, 2024). "This phase 1 study also revealed remarkable inhibition of KAT6A and 6B catalytic activity from both blood PBMCs and on-treatment tumor samples in patients with cancer, indicating an on-target effect." (PMID 38824244, 2024). "According to The Human Protein Atlas, KAT6A is characterized as a cancer-related gene, metabolic protein, transcription factor, proto-oncogene and potential drug target." (PMID 36770785, 2023). "Considering the pivotal role of KATs, proteins such as KAT6A—which is involved in major cellular pathways and in the regulation of transcriptional factors and has an oncogenic nature—are important targets in cancer treatment." (PMID 36770785, 2023). "The KAT inhibition strategy to treat cancer is in its initial stages with very few candidates such as WM-8014 for KAT6A and KAT6B inhibition." (PMID 36770785, 2023). "The pivotal role of KAT6A in major cellular pathways and its oncogenic nature make it an important target in cancer treatment." (PMID 36770785, 2023).
cancer (continued). "The oncogene KAT6A promotes cancer by inhibiting cellular senescence." (PMID 37897503, 2023). "The results showed that KAT6A overexpression promoted HF proliferation, which indicated that KAT6A overexpression may play a tumor-promoting role in the development of cancer." (PMID 33995658, 2021). "KAT6A inhibitors have been reported, and the inhibition of KAT6A shows promise for cancer therapy." (PMID 33995658, 2021). "Our study provides the theoretical basis for the application of targeting KAT6A in cancer therapy." (PMID 33995658, 2021). "Coordination of these deregulated miRNAs may together lead to transcriptional deregulation in cancer via a large network, in which KAT6A and TET3 may also participate." (PMID 29587824, 2018). "For example, the KAT6A promoter is more open specifically in MFD-1 cells (top) although at other loci, exemplified by the KRT8 gene, the chromatin associated with the TSS is more open in both MFD-1 and OE33 cancer cell lines compared to HET1A cells (bottom)." (PMID 27600491, 2016). "Although KATs are often mutated or rearranged to form hybrid fusion proteins in many cancer types, no alterations or mutations were observed in KAT6A, 6B, or 7 in BRM-deficient cancer cell lines." (PMID 25774356, 2014). "Thus, KAT6A inhibitors are being developed for cancer therapy." (PMID 35681732, 2022). "Thus, KAT6A role in tumorigenesis might depend on the type of cancer and on the presence of aberration." (PMID 35681732, 2022). "Thus, KAT6A may both promote and suppress cancer, playing competing roles depending on the cellular context." (PMID 31888644, 2019). "To conclude, both KAT6A and KAT6B have a crucial impact on the tumor proliferation, metastasis, and drug resistance of multiple types of cancers, via regulating the PI3K/AKT signaling axis, the ER signaling pathway, and cell cycle‐related pathways." (PMID 41357671, 2025). "To conclude, aberrations of KAT6A and KAT6B are correlated with cancers, distinct neurodevelopmental syndromes, together with other developmental diseases like craniofacial dysmorphism and skeletal abnormalities." (PMID 41357671, 2025). "LUAD exhibited a particularly high number of 7 mutated genes with significant co-occurrence with CNAs compared to other cancer types – including EGFR, GATA2, GBA, GLI3, KAT6A, KRAS and NOTCH3." (PMID 41415395, 2025). "Aberrant expression of KAT6A and KAT6B in different types of cancer can be attributed to various prototypes of genetic alterations, including fusion, mutation, amplification, and deletion." (PMID 41357671, 2025). "In summary, the findings from this phase 1 study establish KAT6A and KAT6B as druggable cancer targets and provide clinical proof of concept in treating HR+/HER2− mBC." (PMID 38824244, 2024). "Recent pan-cancer analysis of CNV has identified KAT6A and KAT6B as top targets for amplification in different cancers." (PMID 36077605, 2022). "In the COSMIC cancer census gene list, the MYC, NSD3 and KAT6A genes on chr8 have been amplified in cancer." (PMID 32512761, 2020). "In this case, the 5′UTRs of KAT6A and NOTCH2 were identified at a q-value cutoff of 0.05, and both genes were discovered in the CGC, and are regarded as known cancer genes." (PMID 31160636, 2019). "We found that NOTCH2, KAT6A and RALGPS2 are all potential cancer driver genes, demonstrating that this method can help us to find RNA structure-related cancer driver elements." (PMID 31160636, 2019). "Importantly, the frequent molecular dysregulation of KAT6A and KAT6B correlates with survival outcomes of cancers, contributing to the exploration of a wide array of small‐molecule inhibitors against KAT6 catalytic activity." (PMID 41357671, 2025).
cancer (continued). "Thesefindings indicate that targeting KAT6A and KAT6B may provide therapeuticbenefits in cancer treatment." (PMID 39958699, 2024). "However, to the best of our knowledge, no study investigated the correlation between the expressions of KAT6A and SIRT3 in cancer, despite their potential importance in tumorigenesis." (PMID 35422864, 2022). "The MYST family of KATs is primarily localized in the nucleus; however, some studies suggestthat KAT6A, KAT6B, and Tip60 can also locate or translocate into thecytoplasm, as evidenced by immunofluorescence staining and subcellularfractionation analyses in certain cancer cells." (PMID 39958699, 2024). "Importantly, the q-arm carries several cancer-relevant genes such as FGFR1, KAT6A and PCM1." (PMID 34707142, 2021).